TNF (tumor necrosis factor)
Diseases named in the same sentence as TNF in open-access papers (continued):
Sharing a sentence is not in itself a finding about the gene and the disease.
Obesity (continued). "Our results reveal that the depletion decreased TNF-α levels in lung homogenates and recovered lung dysfunctions caused by asthma and obesity." (PMID 25658739, 2015). "It is well established that obesity induced low grade inflammation is associated with elevated levels of pro-inflammatory cytokines such as TNF-α and reduced levels of anti-inflammatory cytokines such as IL-10." (PMID 26588700, 2015). "In human and rodent obesity, increased mRNA expression of TNF is implicated in the induction of insulin resistance through several mechanisms, including inhibition of intracellular signalling from the insulin receptor." (PMID 25938677, 2015). "Actually, IL-6, MCP-1, resistin, and TNF-α are associated strongly with obesity-induced inflammation and obesity-related pathologies." (PMID 26248075, 2015). "Obesity is characterized by hypertrophic adipocytes producing low adiponectin and increased tumor necrosis factor α (TNF-α) levels, which are associated with insulin resistance." (PMID 26834634, 2015). "TNF-α is a pro-inflammatory cytokine involved in the development of obesity-associated fatty liver, and its concentration is increased in genetically obese rodents." (PMID 26438694, 2015). "Several specific inflammatory factors have been linked to both obesity and AD including leptin, TNF-α and IL-6." (PMID 26217222, 2015). "Defects in TGM2 gene are associated with early onset of Type 2 diabetes, and TNF-alpha has been implicated as a causative factor in obesity-associated insulin resistance and the pathogenesis of type 2 diabetes." (PMID 26302420, 2015). "Obesity-related insulin resistance (IR) is also associated with elevated cytokine levels, including tumor necrosis factor (TNF)-α and interleukin (IL)-6, and elevated serum free fatty acid levels." (PMID 26039731, 2015). "Adipose (fat) tissue plays a role in pro-inflammatory cytokine secretion; obesity is associated with an increased number of macrophages, which are responsible for most of the TNF-α and IL-6 cytokine production." (PMID 26340637, 2015). "The most significant alterations of immune markers associated with HFD-induced obesity in serum were those of TNF-α, IL-18 and IL-17A, whose concentrations significantly increased (p<0.001–0.013)." (PMID 26161548, 2015). "As markers of obesity-induced inflammation, the plasma concentration of LPS and TNF-alpha were considered, since metabolic endotoxaemia is associated with obesity, metabolic syndrome and type 2 diabetes." (PMID 26244577, 2015). "Chronic low-grade inflammation and obesity are associated with elevated levels of TNFα and KO has been shown to have a positive influence on inflammation in both high-fat-fed mice and in obese Zucker rats." (PMID 25961320, 2015). "Early during infection (i.e., d3 p.i.), obesity was again associated with reduced production of cytokines IL-13, IL-5, IL-12p70, IFNγ, TNFα, IL6, and IL-1β, as well as IL-28b (IFNλ), IL-17, and IL-15." (PMID 26110868, 2015). "Numerous animal and human studies with T2D patients have positively correlated TNFα with obesity and IR, and have implicated a role for TNFα in the pathogenesis of IR primarily through its postreceptor effects." (PMID 26441826, 2015). "Obesity is associated with elevations in insulin, free insulin-like growth factors (IGFs), and adipocyte-derived factors that include leptin, TNF-alpha, IL-6, and reductions in adiponectin." (PMID 25811460, 2015). "TNFα overexpression is viewed as the hallmark of inflammation in obesity and NAFLD pathology and a major link to insulin resistance." (PMID 26090470, 2015). "Obesity causes hypertrophy of adipose tissue that leads to the release of diverse inflammatory cytokines, such as TNF-α and IL-1β, and these increased cytokines lead to insulin resistance through the inhibition of the insulin receptor signaling pathway." (PMID 26569269, 2015).
Obesity (continued). "Taken together, in the present study, circulating levels of leptin are found to be associated with well defined cardiovascular risk factors such as obesity, triglycerides, insulin and TNF-α in AMI subjects." (PMID 25762868, 2015). "Many authors emphasize associations between obesity and general inflammation with elevated levels of TNFα, IL-6, and leptins." (PMID 25663327, 2015). "By contrast, obesity induced increasing gene expression of molecules characteristic of M1 macrophages, such as those encoding TNF and NOS2, suggesting that diet-induced obesity leads to a change from M2 to M1 polarization." (PMID 26074923, 2015). "Obesity is associated with elevated TNFα adipose tissue production and increased oxidative stress biomarkers, promoting the proinflammatory response in septic patients." (PMID 25244356, 2014). "(ii) Does loss of TNFα function influence adipogenesis in genetic obesity background during development of obesity on a chow diet?" (PMID 24522555, 2014). "Testosterone status and diet-induced obesity were associated with significant regulation of macrophage infiltration, mRNA levels of IL-1β, TNFα, and P0, and activity levels of Na+,K+-ATPase." (PMID 25224590, 2014). "All of this strongly suggests that increased TNFα-associated with obesity, insulin resistance, and hyperinsulinemia can cause an elevation in the cerebral accretion of Aβ or increased neurodegenerative processes." (PMID 24683436, 2014). "TNFα has been among the first inflammatory mediators to be implicated in the induction of insulin resistance in obesity." (PMID 24203314, 2014). "Previous studies reported that leptin secretion is positively correlated with adiposity, and that TNF-α action is implicated in inflammatory response and insulin resistance, at least in obesity." (PMID 24159189, 2014). "Obesity is associated with basic systemic inflammation, characterised by an increase in pro-inflammatory markers such as TNF-α and IL-6." (PMID 25429679, 2014). "At the systemic level, obesity is associated with elevated pro-inflammatory cytokines TNF-a and IL-6, NEFA and basal concentrations of insulin." (PMID 24722524, 2014). "TNF-α was the first cytokine associated with insulin resistance in animals; it is overexpressed in adipose tissue in obesity and decreases with weight loss, being also considered as an important insulin resistance regulator." (PMID 24741627, 2014). "HIV lipodystrophy, familial partial lipodystrophy and obesity have been associated with high circulating levels of TNF-α." (PMID 24958357, 2014). "Jointly, these data support a role for monocyte-expressed Fas in the development of obesity-associated (muscle) insulin resistance in humans potentially via increased release of TNFα into circulation." (PMID 24203314, 2014). "Obesity is often associated with increased markers of inflammation, in part because adipocytes themselves release adipokines, including IL‐6, TNF‐α, and CRP." (PMID 25347862, 2014). "TNF-α seems to play a role in the physiopathology of blood hypertension (BHP) associated with obesity and insulin resistance, as it inhibits insulin dependent glucose uptake by interfering with its signaling." (PMID 24741627, 2014). "TNF α has been implicated for its involvement in all stages of obesity leading to insulin resistance, hypertension, and the metabolic syndrome." (PMID 25258478, 2014). "Increased TNF-alpha production has been observed in adipose tissue derived from obese rodents or humans, and has been implicated as a causative factor in obesity-associated insulin resistance and diabetes mellitus pathogenesis." (PMID 24991532, 2014). "This study aimed to analyse the impact of obesity in type 2 diabetes (T2D) on adipocytokines (adiponectin, leptin and resistin) and inflammatory markers (TNF-α, IL-6 and hsCRP) as cardiovascular risk factors." (PMID 24736687, 2014).
Obesity (continued). "The expression and secretion of leptin, resistin, and TNF-α have been associated with the progression of obesity, while the adiponectin has been shown to be inversely related with obesity and has anti-inflammatory and anti-atherosclerotic properties." (PMID 24932656, 2014). "Expression of adiponectin in adipose tissue is lower in subjects with obesity and insulin resistance than in lean subjects and is associated with higher degrees of insulin sensitivity and lower adipose TNF-α expression." (PMID 24733068, 2014). "Recently, it has been demonstrated that obesity is associated with a low-grade inflammatory process, characterized by increased circulating levels of proinflammatory cytokines such as TNF-α, IL-6, and acute-phase proteins (CRP)." (PMID 24741576, 2014). "The aim of this study was to evaluate the association between obesity, measures of body fat content, and serum TNF-α, IL-6, and IL-10 in cSLE." (PMID 24741576, 2014). "Although these cytokines have been shown to be associated with CVD in other populations, we only observed an association between serum TNF-α levels and obesity, and PBF and total fat mass in trunk region." (PMID 24741576, 2014). "High-sensitivity CRP is a more sensitive inflammatory marker associated with obesity indices than IL-6 and TNF-α." (PMID 24507240, 2014). "Obesity is usually associated with overload of proinflammatory cytokines including IL-6, TNF-α, and MCP-1, MMPs and fatty acid binding protein produced by visceral fat, macrophages, and adipocytes." (PMID 24967393, 2014). "Levels of TNF-α are increased in obesity, indicating a role for this cytokine in the obesity-associated inflammation and particularly in insulin resistance and diabetes." (PMID 24829560, 2014). "These obesity-attributable illnesses have been discovered to have a strong association with inflammatory parameters in plasma such as proinflammatory cytokines (TNF-α and IL-6)." (PMID 24324381, 2013). "Obesity is a low-grade inflammatory state that associates with increased secretion of several proinflammatory cytokines, such as tumor necrosis factor-α and interleukin-6, which stimulate CRP production." (PMID 24634792, 2013). "They used cytokine antibody array to show that BMJ diet supplement reduced plasma levels of some important pro-inflammatory cytokines implicated in obesity-associated adipose tissue inflammation, such as IL-6, TNF-α and MCP-1 in mice with HFD." (PMID 24358329, 2013). "Obesity causes lipotoxicity and adipose tissue dysfunction with excessive production of adipokines like tumor necrosis factor-α (TNF-α) and interleukin 6 (IL-6) IL-1β, all of which are implicated in heart failure and related cardiometabolic complications." (PMID 24454978, 2013). "IL-6, MCP-1, resistin, and TNF-α are associated strongly with obesity-induced inflammation and obesity-related pathologies." (PMID 24049664, 2013). "Since the finding that TNFα is linked to insulin resistance, mechanism of obesity-induced inflammation has been suggested." (PMID 23761785, 2013). "Nevertheless, before establishing a possible cause-and-effect relation among leptin, TNF-α, and IL-12 in the scenario of obesity, additional prospective clinical research is required." (PMID 23986664, 2013). "The tumor-promoting cytokines IL-6 and TNF caused by obesity are involved in the development of hepatic inflammation and steatosis." (PMID 27335818, 2013). "In this study, we found HFD fed mice was under the pathophysiologic condition of inflammation associated with obesity evidenced by high levels of IT-6, TNFα and leptin." (PMID 24143244, 2013). "Circulatory TNFα and IL-6 are believed to be the pivotal cytokines involved in obesity-associated hepatic inflammation." (PMID 24379011, 2013). "Tumor necrosis factor alpha (TNFα) was the first described cytokine to have a relevant role in obesity and an associated insulin-resistant state." (PMID 24416031, 2013).
Obesity (continued). "In this regard, obesity-promoted hepatocellular carcinoma development was dependent on increased production of the cytokines TNF-α and IL-6, which cause hepatic inflammation and activation of the oncogenic transcription factor STAT3." (PMID 24106481, 2013). "In conclusion, obesity associated with increased serum leptin and TNF-α levels enhance eosinophil chemotaxis and adhesion in asthmatic children and adolescents." (PMID 23773659, 2013). "In a similar way that in the case of anthropometric and biochemical parameters of obesity, serum IL-12 showed a significant coefficient of association with circulating levels of TNF-α, a typical inflammatory marker (r = 0.4717, P < 0.0001)." (PMID 23533314, 2013). "Pro-inflammatory cytokines, such as tumor necrosis factor (TNF)-α and interleukin (IL)-1β are implicated in the development of obesity-related systemic inflammation and NAFLD." (PMID 23585904, 2013). "Increased production of TNF-α has also been widely associated with obesity-related insulin resistance and abnormal vascular reactivity, the vasculature being an important target of TNF-α." (PMID 24177571, 2013). "Up to 35% of plasma IL-6 originates from adipose tissue, and other cytokines such as IL-10 and TNF-α are also reported to be elevated in obesity and linked to a wide range of metabolic complications." (PMID 23951156, 2013). "Obesity has been shown to cause an increase in plasma concentrations of a number of proinflammatory markers (e.g., IL-6, TNF-α) that are expressed and released by adipocytes." (PMID 24453416, 2013). "Many current studies have concluded that TNFα actions and contributions to the system are implicated in metabolic disturbances like obesity and insulin resistance." (PMID 24324517, 2013). "That subtle inflammation, including critical expression of TNF-α, is associated with and likely causal for obesity linked T2D insulin resistance and faulty insulin signaling is well appreciated." (PMID 22606220, 2012). "Obesity was associated with inflammation in the mouse mammary gland and was accompanied by elevated levels of TNF-α, IL-1β, and COX-2 in both the mammary gland and visceral fat." (PMID 23272114, 2012). "It is interesting to note that the relationship between apelin and insulin or TNFα during obesity and obesity-associated disorders was still maintained at the end of the aerobic exercise but was dependent on the magnitude of insulin sensitivity." (PMID 23653851, 2012). "Increased expression of TNF-α has been observed in both acute and chronic inflammatory states, including the chronic inflammatory response associated with cancer, obesity, and diabetes." (PMID 22701472, 2012). "The tumor necrosis factor-α (TNF-α) SNP at position -308 G/A has been associated with obesity risk and increased C-reactive protein (CRP) concentrations." (PMID 23176569, 2012). "Tumor necrosis factor-α has been implicated in contributing to insulin resistance in obesity due to its increased expression in adipose tissue." (PMID 23267348, 2012). "Given that chronic inflammation in diet-induced obesity is associated with lipid metabolism, we next measured the plasma levels of proinflammatory cytokines, including TNF-α, IL-6, monocyte chemoattractant protein 1 (MCP-1) and interferon γ (IFN-γ)." (PMID 22720061, 2012). "Deleterious effects of this TNF-α variant allele was previously suggested in a meta-analysis in which individuals carrying the -308 G/A polymorphism had greater risk of obesity and comorbidities." (PMID 23176569, 2012). "In both mice and humans, high fat diet and obesity are associated with increased adipose tissue macrophages, which are responsible for secreting most of the IL-6 and TNF-α produced by adipose tissue." (PMID 22935594, 2012). "The elevated systemic TNF-α that is strongly associated with obesity comes largely from visceral adipose tissue." (PMID 22935594, 2012).
Obesity (continued). "The TNF-α, IL-6 and AdipoQ polymorphisms were selected considering the participation of these cytokines in underlying mechanisms of obesity-related metabolic disturbances, such as inflammation and insulin resistance." (PMID 23176569, 2012). "Biological evidence indicated that high levels of interleukin 6 and tumor necrosis factor, which are associated with obesity, turned healthy cells into malignant ones through chronic low-grade inflammation of the liver." (PMID 23028553, 2012). "TNF-α is inflammatory cytokine predominantly released from macrophages, which implicated in the chronic inflammatory status of both obesity and asthma." (PMID 23056561, 2012). "Obese mice with a TNF-α-/-mutation displayed improved insulin sensitivity and lowered circulating fatty acids, improving obesity-induced glucose tolerance." (PMID 23267348, 2012). "Following treatment with an obesity-associated inflammatory mediator TNFα, the ratio active to total immunodetectable chemerin in adipocyte media increased." (PMID 23227233, 2012). "A proinflammatory cytokine with diverse biological effects, TNF-α plays a critical role in the pathogenesis of obesity-linked insulin resistance." (PMID 22313574, 2012). "Because elevated systemic TNFα has been associated with obesity and type 2 diabetes and TNFα is known to induce insulin resistance in vitro and in vivo, the lowered plasma TNFα in TG mice would therefore be expected to have beneficial effects." (PMID 22384185, 2012). "Since TNFα has been implicated as a link between obesity and insulin resistance this circular loop [(TWEAK)-(miR-715)-(TNFrsf1a)] provides some experimental evidence for this particular miRNA's connection with caloric pathway." (PMID 22245972, 2012). "Obesity in both human and animal models has been associated with increased inflammatory markers, including TNF-α and IL-6." (PMID 22518191, 2012). "The chronic inflammatory response caused by obesity and enhanced production of IL-6 and TNF-α ma also increase the risk not only of HCC but of other cancers." (PMID 22470194, 2012). "IL-6, CRP, and TNF-α are the main inflammatory molecules associated with obesity-related inflammation." (PMID 21599899, 2011). "Activation of TLR4 causes the secretion of IL-6 and TNF-α, supporting the role of LPS in triggering the downstream inflammatory processes associated with obesity, such as metabolic disease." (PMID 22115311, 2011). "Several studies associate obesity with chronic inflammation since blood markers, such as the proinflammatory cytokine interleukin 6 (IL-6) and tumour necrosis factor α (TNFα), are increased in these patients." (PMID 22144986, 2011). "Previous studies reported elevated levels of plasma TNF- α and IL-6 in obese rodent models and in humans, which are implicated in the development of obesity induced insulin resistance and diabetes." (PMID 21083914, 2010). "Obesity in humans and rodents is associated with increased expression of pro-inflammatory cytokines, such as tumor necrosis factor (TNF) α, in white adipose tissue (WAT)." (PMID 20463885, 2010). "Since TNF-α has been linked to obesity associated insulin resistance, we assessed plasma glucose, insulin and HOMA in CONV mice fed HF or LF diet and tested for correlations with ileal TNF-α." (PMID 20808947, 2010). "Increased level of TNF-α in adipose tissue is closely associated with obesity-related complications such as insulin resistance, therefore providing useful therapeutic targets for modulating visceral obesity-related pathologies it is a must." (PMID 20370890, 2010). "As in obesity, aging is frequently associated with increased fat tissue and circulating pro-inflammatory cytokines, including TNFα and IL-6." (PMID 20701600, 2010). "Inactivation of the inhibitor of NFkB kinase beta (IKK2), the main activator of TNF-α-stimulated NFkB activation in myeloid cells, protects mice from the development of obesity-associated insulin resistance." (PMID 20463885, 2010).